MTOR (mechanistic target of rapamycin kinase)
Diseases named in the same sentence as MTOR in open-access papers (continued):
Sharing a sentence is not in itself a finding about the gene and the disease.
glioblastoma (continued). "Exposure of human drug-tolerant glioblastoma cells to hypoxia led to 91% repression of mTOR phosphorylation." (PMID 34136065, 2021). "There are also reports on the role of CCL5 in activating the mammalian target of rapamycin (mTOR) pathway, which has been shown to be critical for the maintenance of GSCs and the survival of mesenchymal glioblastoma tumour cells." (PMID 33803414, 2021). "Our data suggests that the combination of VEGF inhibitors, such as bevacizumab, and mTOR pathway inhibitors, such as temsirolimus, should continue to be considered and tested as potential treatments or adjuncts for treatment of glioblastoma and other tumors." (PMID 34077449, 2021). "NC exhibited inhibition of the malignant behavior via inactivation of the PI3K/Akt/mTOR pathway in glioblastoma cells." (PMID 33288736, 2020). "Therapeutic agents regulate phosphoinositide 3-kinase (PI3K)/protein kinase B (AKT)/mammalian target of rapamycin (mTOR) pathway or autophagy for glioblastoma (GB) treatment." (PMID 33123479, 2020). "We identify effects on the PI3K/Akt/mTOR and other signaling pathways in this glioblastoma model cell system and use the observed gene expression responses of the two compounds to define their potential synergies." (PMID 32946518, 2020). "Collectively, our findings indicate that E2F7 promotes cell proliferation, cell metastasis and tumorigenesis via EZH2-mediated PTEN/AKT/mTOR pathway in glioblastoma." (PMID 32814835, 2020). "RAI14 promotes mTOR-mediated inflammation under inflammatory stress and chemical hypoxia in U87 glioblastoma cell line." (PMID 32228518, 2020). "In particular, constitutive PI3K/Akt pathway activation is a hallmark of glioblastomas; however, results from clinical trials by using PI3K/mTOR inhibitors are disappointing." (PMID 32463592, 2020). "In non-small cell lung cancer (NSCLC) or glioblastoma where EGFR driver mutation (EGFR-mut) and/or gene amplification are prevalent, mTOR activation contributes to disease progression, metastasis and tyrosine kinase inhibitor (TKI) resistance." (PMID 32923403, 2020). "Glioblastoma cells are less likely to resist autophagy, and inhibition of mTOR induces the autophagic process." (PMID 33233671, 2020). "Recent research has found that HIF-1α is activated via the Akt/mTOR pathway, enhancing the migration and invasion of human glioblastoma U87 cells." (PMID 32685545, 2020). "We also demonstrated, for the first time, that E2F7 is involved in PTEN/AKT/mTOR pathway through regulating EZH2 in glioblastoma." (PMID 32814835, 2020). "A combination of Tivantinib, PI3K inhibitor LY294002 and mTOR inhibitor, rapamycin has been shown to largely inhibit the proliferation of glioblastoma cells." (PMID 32887519, 2020). "The suberoylanilide hydroxamic acid (SAHA), an inhibitor of histone deacetylase, induces autophagy through the negative regulation of the AKT/mTOR signaling, and inhibits cell proliferation, promoting apoptosis in glioblastoma CSCs." (PMID 33233671, 2020). "Of particular interest to our study is that reducing mTOR signaling via rapamycin has been documented to decrease glioblastoma viability 16-18." (PMID 33162811, 2020). "PROG also suppresses mTOR, a negative regulator of autophagy, as shown in a rodent model of traumatic brain injury and human glioblastoma cells." (PMID 32466385, 2020). "The mTOR pathway is elevated in the majority of glioblastomas 5, 6 and inhibiting the pathway has apoptosis-inducing effects on cells 16-18." (PMID 33162811, 2020). "Western blot showed that phosphorylation of AKT at Ser473, mTOR at Ser2448, was decreased in glioblastoma cells with E2F7 knockdown and increased in cells with E2F7 overexpression." (PMID 32814835, 2020). "As discussed in Macroautophagy in Glioblastoma, an overall downregulation of mTOR signaling exerted by MA was noted, leading to β-catenin degradation and decrease in WNT signaling." (PMID 33312955, 2020).
glioblastoma (continued). "While a well-known mTOR inhibitor, rapamycin, has been shown to reduce glioblastoma survival, the role of mitochondria in achieving this therapeutic effect is less well known." (PMID 33162811, 2020). "Inhibition of the PI3K/Akt/mTOR signaling pathway represents a potential issue for the treatment of cancer, including glioblastoma." (PMID 33718332, 2020). "From January 2017 to September 2019, about four major clinical trials were published, while currently, there are about 11 ongoing clinical trials based on P13K and mTOR inhibition for glioblastomas." (PMID 32290213, 2020). "mTOR is a master regulator of cell survival and its downregulation by rapamycin has been thought to be key to its apoptosis-inducing effects in glioblastoma." (PMID 33162811, 2020). "Recently in glioblastoma stem-like cells research, mTOR pathway is link to the self-renewal ability and tumorigenicity of CICs." (PMID 32351887, 2020). "Autophagy and the (PI3K-Akt/mTOR) signaling pathway play significant roles in glioblastoma multiforme (GBM) cell death and survival." (PMID 30669284, 2019). "PKCη was shown to promote cell proliferation in glioblastoma cells by acting upstream of Akt and mTOR signaling pathways." (PMID 30781807, 2019). "Our results demonstrated that stellettin B, a marine-sponge-derived triterpenoid, inhibits Akt/mTOR signaling and reduces the survival rate of glioblastoma cells." (PMID 30769863, 2019). "Autophagy induction, mainly through inhibition of the mTOR pathway, exerts anti-proliferative and pro-differentiating effects on glioblastoma stem-like cells." (PMID 31387280, 2019). "The present review aims to dissect those autophagy-related, mTOR-dependent and -independent biochemical pathways that characterize cancer stem cells in glioblastoma." (PMID 31387280, 2019). "Ample laboratory studies suggest that this pathway is vital to the growth and survival of cancer cells, including glioblastoma with hyperactivated PI3K/Akt/mTOR." (PMID 31247000, 2019). "To assess the effect of stellettin B on the Akt/mTOR pathway, we used constitutive Akt-activated glioblastoma cell lines, U87MG and GBM8401, for the following experiments." (PMID 30769863, 2019). "Differential activation of SDF-1/CXCR4 signaling, stem cell specific transcriptional factors, PI3K, Akt, and mTOR have been related to glioblastoma progression and aggressiveness." (PMID 31007847, 2019). "Several clinical trials using mTOR inhibitors to treat brain tumors showed that the clinical value of single or combined treatment of primary or recurrent glioblastoma is unclear." (PMID 31665029, 2019). "In parallel, we also examined the total protein levels of 4E-BP1, following the recommendations of a comprehensive study proposing guidelines for mTOR activation assessment in glioblastoma." (PMID 31258848, 2019). "To confirm the activation of mTOR in the SEGA-like glioblastomas, we analyzed by IHC the phosphorylation of 4E-BP1, which is a direct substrate of mTOR kinase." (PMID 31258848, 2019). "One study also reveals that glutaminase (GLS) and glutamate levels are elevated in glioblastoma after treating with mTOR inhibitor." (PMID 31277692, 2019). "We demonstrated that stellettin B inhibits cell proliferation through the Akt/mTOR pathway and cell mobility through the inhibition of p-Girdin and F-actin interaction in glioblastoma cells." (PMID 30769863, 2019). "The reason is that D-2HG-mediated energy depletion activates AMPK and then blunts protein synthesis and mTOR signaling, leading to a decline of Mcl-1, which sensitizes glioblastoma cells to Bcl-xL inhibition-mediated apoptosis." (PMID 31450721, 2019). "Vengoji and colleagues recently reported that BBR has anti-tumor effects through inhibition of the mTOR-signaling pathway and can induce senescence of human glioblastoma cells by downregulating the EGFR–MEK–ERK signaling pathway." (PMID 31841506, 2019).
glioblastoma (continued). "It has been shown that induction of autophagy by nutrient deprivation or mechanistic target of rapamycin (mTOR) pathway inhibition leads to reduced migration and invasion in glioblastoma cells." (PMID 31126310, 2019). "Further, stellettin B downregulates Akt/Mammalian Target of Rapamycin (Akt/mTOR) and Signal transducer and activator of transcription 3 (Stat3) signaling pathways, which are essential for invasion and angiogenesis in glioblastoma." (PMID 30769863, 2019). "In glioblastoma cells, Akt1 promoted HIF1α translation in a manner that is insensitive to rapamycin or mTOR depletion." (PMID 31817676, 2019). "Here, we explore the impact of the Akt inhibitor MK-2206 alone and in combination with the dual PI3K and mTOR inhibitor PI-103 on the radiation sensitivity of glioblastoma cells." (PMID 30943918, 2019). "A follow-up study showed RapaLink-1 was also a potent inhibitor of both wild-type and active mTOR mutants in glioblastoma cell lines." (PMID 35582282, 2019). "Recently, mTOR was considered to be a master regulator of cell growth and recognized as a good therapeutic target for therapies in glioblastoma." (PMID 31009513, 2019). "For example, proteomics and genomics studies that analyzed changes that occur after treatment with mTOR inhibitors revealed bypass mechanisms related to protein synthesis in Ewing sarcoma cells and glioblastoma." (PMID 31817676, 2019). "In our study, Triciribine and Rapamycin were used to assess the role of inhibiting two different points of the Akt/mTOR pathway in vitro on U251 (glioblastoma) and SH-SY5Y (neuroblastoma) human cell lines and their CSCs." (PMID 30323898, 2018). "Some inhibitors of RTKs/PI3K/AKT/mTOR increase the sensitivity of apoptosis-resistant glioblastoma cells to pro-apoptotic and/or pro-autophagic drugs." (PMID 30486451, 2018). "Moderate cytoplasmic phospho-mTOR and pS70K staining occurred only in primary and recurrent glioblastoma P5." (PMID 29805974, 2018). "Accordingly, palbociclib combined with the mTOR inhibitor everolimus has been recently demonstrated to inhibit aerobic glycolysis in glioblastoma cells." (PMID 29587820, 2018). "Our results revealed that inhibiting either Akt or mTOR via Triciribine and Rapamycin, respectively, would lead to a similar decrease in sphere formation ability in both glioblastoma and neuroblastoma cell lines." (PMID 30323898, 2018). "The mechanistic target of rapamycin (mTOR) drives several physiologic and pathologic cellular processes and is frequently deregulated in different types of tumors, including glioblastoma (GBM)." (PMID 30662577, 2018). "PI3K/AKT/mTOR pathway plays a vital role in survival, proliferation, and progression, migration and invasion of glioblastoma." (PMID 30486451, 2018). "The present study provided a consideration that XHP regulated glioblastoma cell apoptosis through suppressing Akt/mTOR/FOXO1 signaling cascade." (PMID 30046342, 2018). "A subgroup analysis showed that PI3K/AKT/mTOR pathway inhibitor-based therapy significantly improved the PFS in all solid tumour types except glioblastoma." (PMID 29408858, 2018). "The phosphatidylinositol-3-kinase (PI3K)/protein kinase B (Akt) and the mammalian target of rapamycin (mTOR) signaling pathways induce cell proliferation and angiogenesis in glioblastomas and neuroblastomas." (PMID 30373180, 2018). "Despite its nearly universal activation of mammalian target of rapamycin (mTOR) signaling in glioblastoma, tumors are resistant to mTOR-targeted therapy." (PMID 30374421, 2018). "In conclusion, our studies demonstrated that silibinin suppressed YAP expression in addition to inhibition of mTOR pathway in glioblastoma cells." (PMID 29780826, 2018). "Recently, a third-generation mTOR inhibitor which overcomes the resistance to first- and second-generation mTOR inhibitors has been developed and already showed promise by exhibiting a higher efficacy in glioblastomas compared to previous mTOR inhibitors." (PMID 29587439, 2018).
glioblastoma (continued). "PI3K and phospho-AKT expression characterized all tumors, while p-mTOR and pS70K staining occurred only in one glioblastoma with prolonged survival." (PMID 29805974, 2018). "Intriguingly, the PI3K/AKT/mechanistic target of rapamycin (mTOR) signaling was elevated in ~88% of all glioblastomas." (PMID 29149079, 2017). "In this study, we show that NVP-BEZ235, a dual PI3K/mTOR inhibitor, potentiates the effects of irradiation in both adult and pediatric glioblastoma cell lines, resulting in early metabolic changes detected by nuclear magnetic resonance (NMR) spectroscopy." (PMID 28624789, 2017). "This is consistent with previously published results by us and others, using different PI3K/AKT/mTOR inhibitors in various cancer types including adult and paediatric glioblastoma." (PMID 28704425, 2017). "Hyperactivation of the mTOR pathway is considered a common feature in several tumors and represents the major molecular alteration in glioblastoma cells." (PMID 28418837, 2017). "Glioblastoma cells feature mammalian target of rapamycin (mTOR) up-regulation which relates to a variety of effects such as: lower survival, higher infiltration, high stemness and radio- and chemo-resistance." (PMID 28418837, 2017). "The present study improves our awareness of basic mechanisms which relate mTOR activity to the biology of glioblastoma cells." (PMID 28418837, 2017). "For example, the use of FC85, a dual AKT/mTOR inhibitor, induces apoptosis both in glioblastoma cell lines and in GSC-enriched cultures." (PMID 29259986, 2017). "We have identified lactate and choline metabolites as potential non-invasive biomarkers for monitoring the response to PI3K/mTOR pathway inhibitors, both in pediatric and adult glioblastomas." (PMID 28624789, 2017). "Nowadays a number of clinical trials are ongoing to evaluate the effects of mTOR inhibition with rapamycin (or rapalogs) based on the exciting results obtained both in vitro in glioblastoma cell lines and in preclinical in vivo models of GBM." (PMID 29259984, 2017). "The mTOR inhibitor AZD8055 has been shown to synergize with GLS inhibitor 968 in a glioblastoma model." (PMID 28950000, 2017). "Inhibition of miR-381 sensitized glioblastoma cells to temozolomide (TMZ) by inhibiting the mTOR pathway through targeting NEFL." (PMID 28193228, 2017). "The PI3K/Akt/mTOR signalling network is activated in almost 90% of all glioblastoma, the most common primary brain tumour, which is almost invariably lethal within 15 months of diagnosis." (PMID 29184057, 2017). "Collectively, these data indicate that SH-mediated autophagy is attributed to the activation of the JNK pathway and the inhibition of the Akt-mTOR pathway in both human glioblastoma cell lines." (PMID 28891980, 2017). "Although issues like cross-talk signal pathways or tumor heterogeneity tarnished the efficacy of therapy targeted PI3K/Akt/mTOR as we expected, we still believe that it will light up a new way in glioblastoma therapy." (PMID 26967052, 2016). "Hyperactivation of mTOR signaling is reported in glioblastoma thus making it an interesting target for therapeutic intervention." (PMID 26940200, 2016). "A combination treatment in glioblastoma multiforme uses differentiating agents with mTOR pathway inhibitors to target CSCs, thereby targeting the ERK1/2 pathway." (PMID 27891093, 2016). "This underscores the importance of including differentiating agents along with inhibitors of mTOR pathways in the treatment of glioblastoma multiforme." (PMID 27891093, 2016). "mTOR signaling plays crucial roles in apoptosis and autophagy and is recognized as a targeted therapy for glioblastomas." (PMID 27893811, 2016). "In US28-expressing glioblastoma cells we detected elevated levels of active (phosphorylated at Ser-473) Akt, further implicating the involvement of the Akt/mTOR pathway in US28 oncomodulatory signaling." (PMID 27602585, 2016).
glioblastoma (continued). "All these results indicate that TMZ can induce apoptotic cell death of glioblastoma cells through upregulating miR-128 gene expression and that miR-128-inhibited mTOR cascades are involved in TMZ cytotoxicity." (PMID 27893811, 2016). "Both genomic and proteomic investigations showed that there is virtually common activation of the PI3K/Akt/mTOR signaling pathway in human glioblastomas." (PMID 27329594, 2016). "In the present study, we have demonstrated the in vitro efficacy of the dual PI3K/mTOR inhibitor dactolisib, with dose dependent reduction of glioblastoma cell proliferation, increased apoptosis and corresponding reduction of Akt phosphorylation." (PMID 27542970, 2016). "In parallel to transcriptomic alteration, recent studies have identified genomic landmarks of recurrent glioblastomas, including the increased TMZ-induced mutagenesis and the mutations in RB and Akt-mTOR pathways." (PMID 26466313, 2015). "At the molecular level, both the AKT/FOXO3a and AKT/mTOR pathways contribute to miR-1908–mediated malignant phenotype of glioblastoma cells, likely mediated by suppressing PTEN expression." (PMID 26265437, 2015). "Previous studies have shown that SAHA-induced autophagy in glioblastoma stem cells depends the inhibition of mTOR through the inhibition of Akt activation." (PMID 26356821, 2015). "Now, with the improvement of the prognosis by targeting the mTOR, inhibitors have been used for blocking the PI3K-AKT/mTOR signaling pathway and have been preliminarily demonstrated to be an anticancer therapeutic intervention in glioblastoma." (PMID 25854175, 2015). "ROS-mediated PI3K/AKT/mTOR/p70S6K signaling pathways was critical to the effects of cathepsin S on the regulation of autophagy and apoptosis in human glioblastoma cells." (PMID 26058063, 2015). "Most of these genes belong to the cross-talked pathways Ras/Raf/MAPK and PI3K/AKT/mTOR, the two major pathways activated by overexpressed ErbB receptors in glioblastoma cells." (PMID 25365520, 2014). "The phosphoinositide 3-kinase (PI3K)/Akt/mammalian target of rapamycin (mTOR) pathway is frequently activated in human cancer and plays a crucial role in glioblastoma biology." (PMID 24718026, 2014). "Inhibition of PI3K p110α or PI3K p110β also led to impaired anchorage-independent growth, a decreased migratory capacity of glioblastoma cells, and reduced the activation of the Akt/mTOR pathway." (PMID 24718026, 2014). "In conclusion, we have shown that PI3K/mTOR inhibition in pediatric glioblastoma cell lines interferes with glucose and choline metabolism leading to decreases in lactate and choline metabolite levels that are detected by NMR." (PMID 25084455, 2014). "Our findings are in line with a previous report showing a decrease in 13C lactate exchange and LDH expression and activity following PI3K/AKT/mTOR inhibition in adult glioblastoma." (PMID 25084455, 2014). "The two cancer cell lines were chosen because mTOR inhibitors are used to treat glioblastoma and renal carcinoma." (PMID 24009623, 2013). "PTEN, which is frequently mutated in glioblastomas, is a tumor suppressor gene that encodes a dual specificity phosphatase that antagonizes the phosphatidylinositol 3-kinase class I/AKT/mTOR pathway, which is a key regulator of autophagy." (PMID 24349488, 2013). "Further investigation will be required to better understand the role of miR-634 and subsequent mTOR activation in the resistance of Glioblastoma to fenofibrate and to identify other signaling molecules critical to this process." (PMID 24705102, 2013). "Secondly, use of temolozide, a pro-autophagic drug, in glioblastoma in combination with an mTOR inhibitor induced autophagy and cell death." (PMID 23675532, 2013). "Although several studies have been performed aiming to establish molecular profiles that would predict predictive clinical responses towards EGFR and/or mTOR inhibition, a convincing molecular signature for glioblastoma is still elusive." (PMID 22530122, 2012).